SIGLEC11 (sialic acid binding Ig like lectin 11)
Description:
Putative adhesion molecule that mediates sialic-acid dependent binding to cells. Preferentially binds to alpha-2,8-linked sialic acid. The sialic acid recognition site may be masked by cis interactions with sialic acids on the same cell surface. In the immune response, may act as an inhibitory receptor upon ligand induced tyrosine phosphorylation by recruiting cytoplasmic phosphatase(s) via their SH2 domain(s) that block signal transduction through dephosphorylation of signaling molecules.
Tractability: Antibody: UniProt predicts a signal peptide or a membrane-spanning region; its Gene Ontology location is reachable by antibodies, with medium confidence.
Gene: Protein-coding gene on chromosome 19 (49,948,971 to 49,961,172, reverse strand). Ensembl gene ENSG00000161640.
Subcellular location: Membrane
Subcellular location (Human Protein Atlas): Golgi apparatus; Nucleoplasm
Pathways (Reactome):
Immune System: Immunoregulatory interactions between a Lymphoid and a non-Lymphoid cell
Gene Ontology:
Molecular function: phosphatase binding; sialic acid binding
Biological process: cell adhesion
Cellular component: plasma membrane; membrane
Genetic constraint (gnomAD): Loss-of-function variants: 46 observed, 45.58 expected, observed/expected ratio (o/e) 1.01, 90% interval 0.8 to 1.29. The upper end of that interval is the gene's LOEUF score, 1.29, which puts it in group 5 of 6, group 1 being the genes least tolerant of losing a copy. Missense variants: 574 observed, 665.21 expected, observed/expected ratio (o/e) 0.86, 90% interval 0.81 to 0.93. Synonymous variants: 261 observed, 285.43 expected, observed/expected ratio (o/e) 0.91, 90% interval 0.83 to 1.01.
Homologues: Orthologues: macaque SIGLEC11 (77% identical), mouse Siglecg (53% identical), rat Siglec10 (53% identical), macaque SIGLEC16 (51% identical), guinea pig Siglec10 (51% identical), tropical clawed frog siglecl2 (20% identical), tropical clawed frog siglecl1 (18% identical), tropical clawed frog siglecl2 (18% identical), tropical clawed frog siglecl1 (12% identical). Paralogues in human: SIGLEC10 (69% identical), SIGLEC5 (37% identical), SIGLEC8 (29% identical), SIGLEC9 (27% identical), SIGLEC12 (27% identical), SIGLEC7 (27% identical), SIGLEC14 (26% identical), SIGLEC6 (25% identical), SIGLEC16 (22% identical), CD33 (20% identical), SIGLEC1 (19% identical), MAG (15% identical), and 4 more.
Diseases named in the same sentence as SIGLEC11 in open-access papers:
SIGLEC11 is named in the same sentence as 24 diseases in open-access papers, as found by Europe PMC text mining. Sharing a sentence is not in itself a finding about the gene and the disease. The quoted sentences say what the papers report.
Alzheimer disease (2 papers, 2024). A progressive, neurodegenerative disease characterized by loss of function and death of nerve cells in several areas of the brain leading to loss of cognitive function such as memory and language. "Recent studies, have identified SIGLEC-11 as the most significant microglial gene associated with Alzheimer’s disease (AD), following the categorization of AD and dementia-related genes based on their relevance to the disease process." (PMID 39764391, 2024). "Genetic variants of SIGLEC3/CD33, SIGLEC11, and SIGLEC14 have been associated with neurodegenerative diseases such as Alzheimer’s disease, while sialyltransferase ST8SIA2 and SIGLEC4/MAG have been linked to psychiatric diseases such as schizophrenia, bipolar disorders, and autism spectrum disorders." (PMID 38529039, 2024).
glioma (2 papers, 2021). A benign or malignant brain and spinal cord tumor that arises from glial cells (astrocytes, oligodendrocytes, ependymal cells). "In co-cultures with HMC3, both A172 and U87MG cells, showed enhanced Siglec-11/Fc binding capacity when compared to monocultured glioma cells (A172/HMC3: 14.07 ± 1.6 vs. 10.3 ± 1.04 monoculture; U87MG/HMC3: 13.95 ± 1.2 vs. 10.46 ± 0.9 monoculture)." (PMID 33670244, 2021). "More recently, a study showed that dexamethasone/temozolomide-treated glioma displayed higher affinities towards inhibitory Siglec-5 and Siglec-11." (PMID 34827170, 2021). "Additionally, the exposure to Dex or TMZ increased the binding of inhibitory Siglec-5 and Siglec-11 fusion proteins to glioma cells." (PMID 33670244, 2021). "However, changes in the binding of recombinant Siglec-5/Fc and Siglec-11/Fc proteins to glioma cells reflect the sialic acid-related alteration in cell membranes." (PMID 33670244, 2021).
brain cancer (1 paper, 2021). A primary or metastatic malignant neoplasm affecting the brain. "One of them, polysialylated neuronal adhesion molecule (PSA-NCAM), has been described as a marker of brain cancer progression as well as a modulator of brain immunity through Siglec-11 recognition in microglial cells." (PMID 33670244, 2021).
glioblastoma multiforme (1 paper, 2021). "Interestingly, while Siglec-11 mRNA expression decreased in most tumours, the up-regulation in glioblastoma multiforme was observed." (PMID 33670244, 2021).
gonococcal infection (1 paper, 2019). "The presence of Siglec‐11 and Siglec‐16 on the cervical columnar epithelium, the main site of gonococcal infection in females, may play a crucial role in host defense." (PMID 30697344, 2019).
prostate adenocarcinoma (1 paper, 2020). "Also, SIGLEC11 mRNA expression was down-regulated in 19 out of 24 cancer types (except GBM, HNSC, THCA, and sarcoma [SARC], prostate adenocarcinoma [PRAD]), and SIGLEC15 was up-regulated in 18 out of 24 cancer types (except BRCA, KIRC, LUSC, PRAD, thymoma [THYM], and skin cutaneous melanoma [SKCM])." (PMID 33240817, 2020).
thyroid cancer (1 paper, 2024). "The role of SIGLEC10 and SIGLEC11 genes in thyroid cancer is not yet investigated." (PMID 38338696, 2024).
tumor (6 papers, 2011 to 2023). "One DEE (ENSE00001756179) of SIGLEC11 was significantly up-regulated in tumor tissue (P<0.001), while another DEE (ENSE00001616306) was significantly down-regulated (P<0.001)." (PMID 22043308, 2011). "Even more crucial, though, will be to establish valid systems to study the physiological role of Siglec-16 and its engagement as potentially activating counterpart of Siglec-11 in responses to polySia released under neuroinflammatory conditions, or presented, e.g., on the surface of tumor cells." (PMID 37171513, 2023).
cancer (5 papers, 2010 to 2024). A tumor composed of atypical neoplastic, often pleomorphic cells that invade other tissues. "Among them, Sialic acid-binding immunoglobulin-like lectins 10 and 11 (SIGLEC10, SIGLEC11) and Keratin-associated protein 5 (KRTAP5-3) transcripts, genes known to be involved in cancer progression, turned out to be up-regulated only in TPC-1-exo." (PMID 38338696, 2024). "Although several studies have reported Siglec-11 or -16 in mediating microglial activities, there are fewer studies related to various cancers." (PMID 34827170, 2021). "In terms of our understanding of Siglec-11 and Siglec-16 in cancer, it still remains unclear." (PMID 34827170, 2021). "For example, the roles of inhibitory Siglec-11 and Siglec-XII in myeloids still remain an enigma in many cancers." (PMID 34827170, 2021).
infection (4 papers, 2019 to 2023). The state of being infected such as from the introduction of a foreign agent such as serum, vaccine, antigenic substance or organism. "We hypothesize that N. gonorrhoeae engages the inhibitory Siglec‐11, which downregulates the pro‐inflammatory response and enables the bacteria to escape immune detection and establish asymptomatic infection." (PMID 30697344, 2019). "Binding to the inhibitory receptors Siglec‐3, Siglec‐5, Siglec‐9, and Siglec‐11 suppresses the pro‐inflammatory response, which could contribute to decreased clearance of infection and contribute to the relative paucity of symptoms." (PMID 30697344, 2019). "Thus, SIGLEC11 and DNAL4 appear to contribute to cell migration and infiltration to site of infection during TB." (PMID 36275677, 2022).
SIGLEC11 also shares sentences with these, for which no sentence is quoted: neurodegenerative disease (2 papers); autism spectrum disorder (1); bipolar disorder (1); dementia (1); Ewing sarcoma (1); fibromatosis (1); gastric cancer (1); meningitis (1); metastatic disease (1); psychiatric diseases (1); sarcoma (1); schizophrenia (1); skin cutaneous melanoma (1); thymoma (1).